CGB5 (chorionic gonadotropin subunit beta 5)
Description:
Beta subunit of the human chorionic gonadotropin (hCG). hCG is a complex glycoprotein composed of two glycosylated subunits alpha and beta which are non-covalently associated. The alpha subunit is identical to those in the pituitary gonadotropin hormones (LH, FSH and TSH). The beta subunits are distinct in each of the hormones and confer receptor and biological specificity. Has an essential role in pregnancy and maternal adaptation. Stimulates the ovaries to synthesize the steroids that are essential for the maintenance of pregnancy.
Synonyms: CGB; HCG
Gene: Protein-coding gene on chromosome 19 (49,043,848 to 49,045,311, forward strand). Ensembl gene ENSG00000189052.
Subcellular location: Secreted
Pathways (Reactome):
Gene expression (Transcription): TFAP2 (AP-2) family regulates transcription of growth factors and their receptors
Metabolism of proteins: Glycoprotein hormones
Gene Ontology:
Molecular function: protein binding; hormone activity
Biological process: apoptotic process; cell-cell signaling; female gamete generation; G protein-coupled receptor signaling pathway; hormone-mediated signaling pathway; signal transduction; cell communication; signaling
Cellular component: extracellular region; pituitary gonadotropin complex
Genetic constraint (gnomAD): Loss-of-function variants: 2 observed, 6.39 expected, observed/expected ratio (o/e) 0.31, 90% interval 0.13 to 0.98. That is too few expected variants to judge how well the gene tolerates losing a copy. Missense variants: 47 observed, 147.45 expected, observed/expected ratio (o/e) 0.32, 90% interval 0.25 to 0.41. Synonymous variants: 25 observed, 57.45 expected, observed/expected ratio (o/e) 0.44, 90% interval 0.32 to 0.61.
Homologues: Orthologues: macaque CGB8 (80% identical), Drosophila melanogaster Gpb5 (16% identical). Paralogues in human: CGB3 (100% identical), CGB8 (100% identical), CGB7 (98% identical), CGB2 (97% identical), CGB1 (92% identical), LHB (70% identical), TSHB (30% identical), FSHB (26% identical), GPHB5 (22% identical).